INS (insulin)
Diseases named in the same sentence as INS in open-access papers (continued):
Sharing a sentence is not in itself a finding about the gene and the disease.
Obesity (continued). "However, obesity is not always sufficient to cause insulin resistance, as 30–40% of individuals with a Body Mass Index greater than 35kg/m2 have normal insulin sensitivity determined by the hyperinsulinemic-euglycemic clamp." (PMID 25835281, 2015). "The mechanistic link between obesity, DM, and adipose tissue inflammation was first proposed based on the finding that the level of the proinflammatory adipokine TNFα was increased in adipose tissue of obese rodents and humans and that its blockage led to improvement in insulin sensitivity." (PMID 26578976, 2015). "Also, it has been suggested that the link between obesity and BC outcome could be due to increased endocrine signaling involving insulin and insulin-like growth factors (IGFs)." (PMID 26100469, 2015). "Because of the prevalence and devastating health consequences of obesity, it is important to gain a better understanding of factors that regulate fat storage in insulin sensitive tissues, particularly since lipids have been shown to disrupt insulin signaling and promote insulin resistance." (PMID 26176546, 2015). "Our data, in line with one previous study of obese individuals, suggest that the insulin-sensitizing effects of female sex may be blunted in the context of severe obesity, or that insulin-desensitizing mechanisms in severe obesity may overwhelm the protective mechanisms that exist in lean women." (PMID 26635731, 2015). "The aim of this study was to investigate GH after OG in relation with adiposity, insulin secretion and action, and ghrelin secretion in obese and healthy women, to further elucidate the mechanism of GH secretion after OG and the altered GH secretion in obesity." (PMID 25782001, 2015). "Magnetic resonance spectroscopy studies have shown that IMCL levels vary with insulin sensitivity and obesity, which is a common clinical picture in the older adult, and that inactivity combined with overconsumption of fat can have detrimental effects on muscular insulin sensitivity." (PMID 25945152, 2015). "Hence, better understanding of FPLD, a natural single-gene model of MS, could be the key to unlock leptin resistance in obesity, allowing leptin to perform its insulin-sensitizing function." (PMID 25859279, 2015). "Thus, we suggest that fasting insulin in early childhood is a predictor of weight gain during late childhood (from 5 to 10 years of age), but in adults, hyperinsulinemia is more likely secondary to obesity." (PMID 26047327, 2015). "Obesity-induced activation of β-cell autophagy is considered as a compensatory response, providing cells with a safety mechanism to eliminate damaged mitochondria and/or other cellular components and to avoid cell apoptosis under insulin-resistant states and high FFA concentrations." (PMID 26445593, 2015). "A Finnish study of identical twins who were either concordant or discordant for obesity showed that, independent of genetic factors, obesity was associated with poor fitness, low insulin sensitivity, and decreased transcript levels of genes involved in mitochondrial OXPHOS pathways." (PMID 26322975, 2015). "Therefore, we hypothesized that the anti-obesity and insulin-sensitizing properties of MnTBAP are mediated by HO-1." (PMID 26397111, 2015). "Furthermore, obesity is associated with an enhanced insulin response to glucose in non-diabetic individuals, and recent histological studies have revealed obesity is associated with a 50 % increase in β-cell mass." (PMID 25982967, 2015). "Obesity might impact breast tumor development via increased estradiol production in adipose tissue in postmenopausal women, higher insulin levels, cellular interaction of leptin with insulin, and a constant pro-inflammatory state." (PMID 25884832, 2015).
Obesity (continued). "It is well known that an increase in adipokine production can influence glucose metabolism, insulin sensitivity and inflammation, and this finding could represent a molecular link between obesity and the development of diabetes mellitus, metabolic syndromes and cardiovascular diseases." (PMID 25621503, 2015). "Thus, the CORT-treated Caps2 KO mice used in the present study may serve as a useful model for investigating the mechanisms of CORT and insulin in depression and obesity." (PMID 25754523, 2015). "Interestingly, lipolytic enzyme expression, particularly ATGL, appears to be more associated with insulin sensitivity rather than obesity." (PMID 25866768, 2015). "Additionally, the IGF-1 receptor is unlikely to be activated at the elevated insulin levels that are associated with obesity." (PMID 25780937, 2015). "Hence, we originally hypothesized that lacking NOD2 detection of this type of PGN (i.e., MDP) would improve insulin sensitivity during obesity." (PMID 25666722, 2015). "This individual might have healthy insulin sensitivity despite the obesity." (PMID 26042523, 2015). "In addition, skeletal muscle respiratory uncoupling can improve insulin sensitivity in obesity." (PMID 26064426, 2015). "Therefore, either an increase or a decrease in striatal insulin sensitivity could contribute to pathological eating, resulting in binge eating and/or obesity." (PMID 26503322, 2015). "Though the knowledge about the relationship of obesity, insulin and cancer increases extensively, but the applications of experimental findings to clinic are scarce with regard to the complicated changes of metabolism in obesity and the vital functions of insulin in body." (PMID 26084465, 2015). "The mammalian target of rapamycin (mTOR) pathway may represent another important biological mechanism linking telomeric aging to obesity, because mTOR pathway integrates insulin and nutrient signaling in numerous cell types and enhanced mTOR signaling has been implicated in cellular senescence." (PMID 24861044, 2014). "Hence, obesity is a remarkably heterogeneous disorder, as evidenced by the occurrence of a subset of obese persons who are insulin sensitive, and a subset of normal-weight people who are insulin resistant." (PMID 25326814, 2014). "Furthermore, in SFRP5-deficient mice, JNK1 loss reverses the impaired insulin sensitivity and increased adipose inflammation, suggesting that a deficiency of SFRP5 promotes obesity-induced inflammation and metabolic dysfunction via activation of JNK1 in adipose tissue." (PMID 24733068, 2014). "However, CRC in the obesity / T2D context involves higher morbidity and mortality risk, due to induced increase in plasma insulin, IGF-1 and adipo/cytokines that promote cell survival, being further increased by treatment with insulin or β-cell secretagogues." (PMID 25375205, 2014). "Furthermore, recent studies have shown that induction of inflammation in the hypothalamus results in experimental obesity, resistance to the anorexigenic hormone leptin, peripheral insulin resistance and defective regulation of food intake and energy expenditure." (PMID 24675731, 2014). "However, the sustained availability of nutrients and insulin that is seen in obesity may be facilitating FGF-21 expression." (PMID 24465939, 2014). "Insulin regulation may be the mechanism linking obesity and pancreatic cancer." (PMID 24454807, 2014). "In addition to their role in growth, cellular differentiation and homeostasis Retinoid X Receptors (RXR) regulate multiple physiological and metabolic pathways in various organs that have beneficial glucose and lipid (cholesterol) lowering, insulin sensitizing and anti-obesity effects." (PMID 25143786, 2014). "The accuracy of proxy measures of insulin sensitivity may vary depending on obesity status." (PMID 24868538, 2014).
Obesity (continued). "However, related factors and underlying mechanisms for these paradoxical associations between obesity and insulin sensitivity or NW and insulin resistance have not been clarified." (PMID 24872812, 2014). "However, increased tissue expression due to other pathological conditions than muscular dystrophy, such as aging, obesity and treatment with insulin or leptin, might affect serum levels of CA3." (PMID 24920607, 2014). "However, further studies are required to determine whether intranasal insulin has antidepressant effects in depressed individuals and, if so, whether this action is maintained in obesity." (PMID 25225489, 2014). "Furthermore, in a study investigating diet-induced obesity, researchers found that inhibition of PDE10A, either through genetic deletion or pharmacological blockade, substantially increased weight loss and insulin sensitivity, while reducing adiposity in mice fed on a Western-style diet." (PMID 25297556, 2014). "Rodent models of HF diet-induced obesity are characterized by inflammation in both peripheral tissues and in the hypothalamic regions critical for energy homeostasis, which is considered an important mechanism linking obesity to glucose intolerance, insulin resistance and leptin resistance." (PMID 24675731, 2014). "Additionally, overweight and obesity, which were found in approximately 31% of the patients, were not directly associated with any insulin therapeutic regimen." (PMID 24920963, 2014). "Additionally, we also observed that rs3480 had a trend towards association with HDL and LDL levels in the overweight/obesity participants, rather than fasting insulin values, which is not consistent with the latest study performed in Japan." (PMID 25369206, 2014). "It is probable that the cross-talk between macrophages and adipocytes may induce a vicious cycle of monocyte recruitment and also M1 macrophage polarization, thereby increasing the inflammatory potential and reducing insulin sensitivity of adipose tissue in obesity." (PMID 24918199, 2014). "It is still not known though, whether aberrations in insulin signaling in obesity are cause or consequence of an impaired browning process or both." (PMID 25313899, 2014). "The reason for starting the obesity, insulin sensitivity, bone density, and depression studies was the hypothesis that high doses of vitamin D (20 000–40 000 IU per week) would have beneficial effects even in a fairly vitamin D sufficient population as the one in Tromsø, northern Norway." (PMID 23577264, 2013). "Thus, decreased insulin action may be one of the possible mechanisms by which obesity affects bone mass." (PMID 23510224, 2013). "After 16 weeks on a high fat diet, control DIO animals develop obesity, mild hyperglycemia, hyperinsulinemia, hyperleptinemia, and increased ectopic fat storage (notably hepatic steatosis), all reflecting the establishment of the metabolic syndrome and an insulin resistant state." (PMID 23781256, 2013). "Obesity exacerbates age-related declines in a range of cognitive abilities (e.g., executive function, memory, and processing speed) by altering adipose secretions, elevating triglyceride level, and impairing insulin regulation to affect structural and functional brain changes in the aging process." (PMID 24391586, 2013). "Therefore, we investigated the associations between changes in adiposity, including SFAT and VFAT evaluated using computed tomography, and changes in insulin secretion and sensitivity as well as CVD risk factors in 196 Japanese participants with obesity over a 1-year period." (PMID 23483954, 2013). "Obesity is also associated with BMD because of the conversion of androgen to estrogen, which improves bone mass in both men and women and maintains healthy plasma levels of insulin and regulating factors including insulin-like growth factor-1, leptin, and adiponectin." (PMID 24222888, 2013).
Obesity (continued). "Obesity-induced pancreatic β-cell death is regulated, at least in part, by the NLRP3 inflammasome, as demonstrated in NLRP3-deficient mice in late-stage obesity, where the ablation of NLRP3 is associated with reduced cell death and increase in pancreatic islet size and local insulin levels." (PMID 23843683, 2013). "Ghrelin may also improve endothelial function mimicking phosphoinositol 3-kinase-dependent actions of insulin to stimulate production of NO by endothelial cells and restoring the endothelin 1/nitric oxide balance in patients with obesity-related MetS, as observed by Tesauro and coworkers." (PMID 24288531, 2013). "Obesity and exogenous insulin may contribute to these results." (PMID 23383010, 2013). "Obesity, especially the abdominal or visceral type, plays a fundamental role in the pathophysiological mechanism of metabolic syndrome, given that it triggers the insulin resistance pathway as result of excessive free fatty acid accumulation in the blood circulation." (PMID 24141291, 2013). "Thus, the collection of our data in this work, together with our recent findings, demonstrated that the benefits of OXT in treating metabolic diseases are multi-faceted, range from obesity control to body weight-independent improvements of insulin sensitivity and insulin secretion." (PMID 23700406, 2013). "Thus, TBK1 and IKKε appear to co-opt insulin targets to conserve energy during obesity." (PMID 24368730, 2013). "Thus, obesity-induced IL-6 secretion may reflect a mechanism to increase insulin production in the obese insulin resistant state." (PMID 24455420, 2013). "However, it will be important to determine if intranasal insulin has antidepressant effects in depressed individuals and, if so, whether this action is maintained in obesity." (PMID 24109426, 2013). "The accumulation of fat, resistance to insulin, and secretion of glucocorticoids observed during pregnancy, as well as the reduction in ovulation cycles in multiparous women, may be factors in the correlation between obesity and parity." (PMID 24228934, 2013). "Additional evidence for this assumption comes from its demonstrated ability to increase postprandial thermogenesis and energy expenditure, suggesting that insulin may improve obesity and metabolic syndrome not only through its anorectic properties, but also through thermogenesis." (PMID 23135822, 2013). "It has been reported that impaired insulin clearance is a major determinant of hyperinsulinemia in obesity after an oral glucose load, and that weight loss, per se, primarily increases insulin clearance without affecting insulin resistance or insulin secretion." (PMID 24194886, 2013). "The lack of impact of the modified diets on insulin and nitric oxide levels in serum and on obesity index observed in this study could be caused by a too-short experimental period of 6 weeks." (PMID 23179349, 2013). "However, the molecular basis of improved insulin sensitivity by activation of this “pro-obesogenic” receptor is incompletely understood, especially considering that obesity and T2D do not represent states of PPARγ deficiency." (PMID 22745632, 2012). "To conclude, we developed a rapid ELISA and show that Adv36 infection is associated with pediatric obesity, severe obesity in adult females and lower levels of blood lipids, and that those infected have a tendency for increased insulin sensitivity in non-diabetic Swedish individuals." (PMID 22848557, 2012). "So it is not surprising that the RGS5 KO mice showed weakened insulin sensitivity because obesity and obesity associated higher levels of lipids and inflammation in circulation and tissues can directly and indirectly destroy insulin signaling in multiple sites." (PMID 22272317, 2012).
Obesity (continued). "Here we show that, in a mouse model of diet-induced obesity, partial substitution of the fatty acid component of the diet by flax seed oil (rich in C18:3) or olive oil (rich in C18:1) corrects hypothalamic inflammation, hypothalamic and whole body insulin resistance, and body adiposity." (PMID 22279596, 2012). "In this regard, obesity is also a neurobehavioral disorder, with the coupling of energy intake and expenditure being tightly regulated by hypothalamic factors, the hypothalamus mediating exercise-induced appetite suppression, and exercise sensitizing the hypothalamus to leptin and insulin." (PMID 22808000, 2012). "Endothelial and microvascular dysfunction are present in obese subjects and represent important factors in metabolic disturbances, since they could influence both vascular resistance and insulin-mediated glucose disposal, contributing to hypertension and insulin resistance in obesity." (PMID 22523672, 2012). "Insulin and leptin levels were significantly lower, and adiponectin levels were higher in the two meals per day group than in the FF group, suggesting that restricted feeding with two meals a day is remarkably effective for protecting against obesity and metabolic syndrome." (PMID 22587351, 2012). "OE-NPYDBH female mice showed a more pronounced diet-induced obesity, glucose intolerant, and insulin resistant phenotype on a Western-type energy-dense diet than their WT littermates that could not be explained by increased feeding, decreased activity, or impaired thermogenesis." (PMID 23118773, 2012). "The results of the present study clearly show that enlarged abdominal adipose cells are associated with reduced systemic insulin sensitivity irrespective of whether obesity is present or not." (PMID 22992414, 2012). "Second, while we might expect this observed reduction in leptin/insulin sensitivity to result in increased dopamine function, analogous to reduced leptin/insulin signals in food-restriction, most studies report decreased dopamine function in obesity." (PMID 22833718, 2012). "In accordance, in a chronological model of diet induced obesity in rats, mitochondrial oxidative capacity first presented a compensatory increase, whereas mitochondrial dysfunction was a late event, only appearing after changes in lipid metabolism and insulin sensitivity had occurred." (PMID 22359625, 2012). "Therefore, it is plausible to suggest that, in obesity, the impact of high levels of circulating insulin during ischaemia and reperfusion could overshadow myocardial susceptibility to ischaemia-reperfusion injury." (PMID 23125848, 2012). "Consequently, we hypothesized that high BMI (i.e., obesity) is the most critical factor that is inversely correlated with serum amylase, and that insulin inactivity is a putative secondary factor that regulates the observed association." (PMID 22748134, 2012). "In conclusion, our study shows that mice with a mutation in the circadian clock gene Per2 have compromised insulin signaling, associated with lower hepatic glycogen content and decreased vascular endothelial function, but no increased predisposition to obesity." (PMID 22934083, 2012). "Some hypotheses have indicated that obesity is involved in metabolic abnormalities, in which insulin and insulin-like growth factors may distort the normal balance between determinants of cell proliferation, differentiation, and apoptosis, and thus may promote carcinogenesis." (PMID 23028553, 2012). "In that respect it might be noteworthy to mention that also normal healthy mice on a chow-diet fail to improve their insulin sensitivity upon resveratrol supplementation, arguing that resveratrol might only be effective under metabolic stress conditions such as obesity or diabetes." (PMID 22436213, 2012).